ABCG2 (ATP binding cassette subfamily G member 2 (JR blood group))
Diseases named in the same sentence as ABCG2 in open-access papers (continued):
Sharing a sentence is not in itself a finding about the gene and the disease.
brain tumors (31 papers, 2010 to 2025). "The expression of ABCG2 has been linked to the effectiveness of chemotherapy and radiotherapy, also in patients with brain tumors." (PMID 38542090, 2024). "For example, constitutive overactivity of the PI3K/Akt pathway induces ABCB1 and ABCG2 expression and their associated proteins’ translocation to the plasma membrane of brain microvasculature endothelial cells, which increases drug resistance of brain tumors." (PMID 36973040, 2023). "It is important to note that the cell lines or tumors used in the described studies did not include NSCLC, but they do give an indication about the role of ABCB1/ABCG2 in brain tumors and metastases in general." (PMID 40893689, 2025). "The advancement of novel drug delivery systems capable of circumventing ABCG2-mediated drug efflux at the BBB holds the potential to radically transform the treatment paradigm for brain tumors." (PMID 38542090, 2024). "Another epigenetic pathway involves melatonin, a hormone that controls the sleep-wake cycle and methylates the ABCG2 promotor, which ultimately leads to decreased ABCG2 protein levels in brain tumor stem cells." (PMID 36973040, 2023). "Down-regulated DEGs in recGBM included genes involved in cell proliferation (EGFR), possibly brain tumor cell growth (BCAN), deadenylation of mRNA, which is linked to neurodevelopmental disorders (CNOT2), and multi-drug resistance (ABCG2)." (PMID 37189838, 2023). "An upregulation of ABCG2 was further shown to reduce the efficacy of PDT in brain tumors, while its inhibition increased both intracellular PpIX levels and PDT efficacy." (PMID 36612300, 2023). "This potentially applies to a range of small-molecule kinase inhibitors, which are dual ABCB1/ABCG2 substrates and which are discussed as potential treatment for brain tumors." (PMID 31832814, 2019). "This in vivo effect was demonstrated both in terms of tumor growth (bioluminescence imaging and tumor proliferation) and apoptosis (TUNEL), reminiscent of reported effects of ABCG2 in high-grade brain tumors." (PMID 26981778, 2016). "The mRNA level of ABC transporter ABCG2 was lower in malignant glioma cells in the brain tumor that exhibited strong fluorescence of PpIX after ALA treatment, whereas the surrounding cells emitted weak and vague fluorescence." (PMID 24310600, 2011). "It is of great interest to develop potent ABCG2-inhibitors that can be applied to PDD for brain tumor therapy." (PMID 24310600, 2011). "The mRNA level of ABC transporter ABCG2 was found to be significantly lower in malignant glioma cells in the brain tumor that exhibited strong fluorescence of PpIX after ALA treatment, whereas the surrounding normal cells emitted weak and vague fluorescence." (PMID 21188243, 2010). "Down-regulated DEGs in recGBM were involved in cell proliferation (EGFR) and possibly brain tumor cell growth (BCAN), deadenylation of mRNA, which is linked to neurodevelopmental disorders (CNOT2), multi-drug resistance (ABCG2), and immune-related processes (GZMK)." (PMID 37189838, 2023). "ABCB1 and ABCG2 may also be overexpressed in the membrane of brain tumor cells, which may thus form a second barrier to the effective treatment of brain tumors." (PMID 31832814, 2019). "Interestingly, the activation of CAR by the CITCO agonist increased ABC-transporter expression (Abcb1 and Abcg2) in blood-brain barrier and inhibited growth and expansion of brain tumour stem cells via inducing cell cycle arrest and apoptosis." (PMID 29137141, 2017). "In addition, we have also found that ABCG2 expression was down-regulated to some extents in malignant glioma of human brain tumors." (PMID 24310600, 2011). "Indeed, we have also found that ABCG2 expression was downregulated in malignant glioma of human brain tumor." (PMID 21188243, 2010).
brain tumors (continued). "Furthermore, to investigate the impact of efflux pumps on OMA’s PK profile and accumulation in the brain tumor tissue, we assessed the affinity of this drug for the human P-gp (ABCB1) and BCRP (ABCG2) transporters and the murine variants (Abcb1a and Abcg2) using a Transwell filter transporter assay." (PMID 39770529, 2024). "Chemotherapy of primary and secondary brain tumors is often unsuccessful, in part because ABCB1 and ABCG2 at the blood-brain barrier restrict access to a wide range of anticancer drugs to the brain and impair their efficacy." (PMID 36973040, 2023). "Our data suggest that the investigated brain tumors had an intact BBTB, which is impermeable to anticancer drugs, which are dual ABCB1/ABCG2 substrates." (PMID 31832814, 2019). "Pharmacological inhibition of efflux transporters at the BBB has also been proposed for a more effective treatment of brain tumors with anticancer drugs, for which brain distribution is limited by ABCB1/ABCG2-mediated efflux transport." (PMID 31832814, 2019). "For example, it has been suggested that ABCG2, FECH, and HO‐1 could serve as indicators of treatment outcome for ALA-PDT of brain tumors, while in HNC, STAT3 could be used as a molecular marker of cumulative photoreaction therapy monitoring." (PMID 34302323, 2021). "A combination of MLT and chemotherapeutic drugs exhibited a synergistic toxic effect on A172 malignant glioma cells and brain tumor stem cells via downregulation of the expression and function of adenosine triphosphate (ATP)-binding cassette transporter ABCG2/BCRP." (PMID 32545820, 2020). "In this exploratory study, we used PET imaging to assess regional brain delivery of [11C]tariquidar as a small-molecule model ABCB1/ABCG2 substrate in patients with non-contrast-enhancing brain tumors." (PMID 31832814, 2019). "We performed positron emission tomography imaging with the radiolabeled ABCB1 inhibitor [11C]tariquidar, a prototypical ABCB1/ABCG2 substrate, in seven patients with non-contrast -enhancing brain tumors (WHO grades I–III)." (PMID 31832814, 2019). "We found very low brain delivery of the model ABCB1/ABCG2 substrate [11C]tariquidar in patients with non-contrast-enhancing brain tumors without significant differences between tumor and tumor-free brain tissue." (PMID 31832814, 2019). "The best strategy for an effective treatment of brain tumors may thus be the development of drugs with good passive permeability which are not subject to ABCB1/ABCG2-mediated efflux transport at the BBTB." (PMID 31832814, 2019). "As opposed to these previous studies, we examined in the present study patients with non-contrast enhancing, low- to high-grade brain tumors and used a radiolabeled model ABCB1/ABCG2 substrate instead of a drug which is used for treatment of tumors." (PMID 31832814, 2019).
osteosarcoma (30 papers, 2010 to 2025). A usually aggressive malignant bone-forming mesenchymal neoplasm, predominantly affecting adolescents and young adults. "In a three-dimensional osteosarcoma model, the increased expression of several drug-resistance-related genes (Bcl2, Abcb1, Abcg2, Nanog, Sox2) was closely associated with heightened glutamine metabolism." (PMID 41300631, 2025). ", which included 59 osteosarcoma patients, ABCG2 rs2231142 was found to be significantly associated with a longer half-life time of methotrexate." (PMID 36536332, 2022). "CHA59, Saos-2, and HuO9 were immunoprobed for the expression of cell surface markers (CD133, CD24, CD166, CD326, CD44, ABCB1, ABCC1, ABCG2) previously reported to be associated with TSCs and/or osteosarcoma." (PMID 22870217, 2012). "The analysis of the expression pattern in 59 osteosarcomas showed that IGF1R expression is highly correlated with ABCG2 expression and with CD44 expression in osteosarcoma patients under 10 years old." (PMID 35785191, 2022). "This study aimed to reveal the role of ABCG2 in the development of chemotherapy resistance and the prognosis of osteosarcoma (OS)." (PMID 33509236, 2021). "A prospective candidate gene study investigating the relation of genetic variants and HD-MTX pharmacokinetics in osteosarcoma patients identified statistically significant associations between MTX clearance and variants in ABCG2 and UGT1A." (PMID 32903464, 2020). "This family includes P-glycoprotein (P-gp), multidrug resistance-associated protein (MRP1 ABCC1 and MRP2 ABCC2), and breast resistance-associated protein (BCRP or ABCG2), all of which have been found to contribute to multidrug resistance in osteosarcoma." (PMID 32961800, 2020). "The contribution of NANOG and ABCG2 in patient-derived osteosarcoma cells resistance to methotrexate still needs to be clarified." (PMID 28934267, 2017). "Other stem cell markers, including CD133, Ki-67, and ABCG2 have been used to sort osteosarcoma stem cells." (PMID 27223261, 2016). "Cox regression analysis of association between ABCB1 C3435T, ABCG2 C421A and ABCC3 C-211T polymorphisms and the survival of osteosarcoma were showed in Table-IV." (PMID 25097538, 2014). "For example, Osteosarcoma CSCs were enriched for ABCG2, a member of ABC transporter, and showed increased drug resistance and metastasis." (PMID 26932376, 2014). "In this study, we planned to investigate the role of three genetic polymorphisms (ABCB1 C3435T, ABCG2 c421A, and ABCC3 C-211T) in response to chemotherapy and overall survival of osteosarcoma patients." (PMID 25097538, 2014). "Both mouse and human DP osteosarcoma cells had increased expression of ABCG2 and CXCR4 compared to DN cells." (PMID 20979639, 2010). "Additionally, an increased expression of drug efflux transporters ABCB1 and ABCG2 was observed in osteosarcoma cancer stem cells." (PMID 36769824, 2023). "In particular, ABCG2 expression has been used to identify a drug-resistant side population or TSCs in a variety of tumors, such as pulmonary, liver, pancreatic, colon tumors, and osteosarcoma." (PMID 22870217, 2012). "Identification of ABCA5 and CBX3 in TSC-enriched spheres fulfilled our goal of finding osteosarcoma biomarker candidates that could be used in combination with already known markers, such as ABCG2 and ALDH." (PMID 22870217, 2012). "Four members of ABC family have been shown to contribute to multidrug resistance in osteosarcoma, including MDR1 (also called P-glycoprotein, P-gp or ABCB1), multidrug resistance-associated protein 1 and 2 (MRP1/ABCC1 and MRP2/ABCC2), and breast cancer resistance protein (BCRP/ABCG2)." (PMID 35955749, 2022). "Therefore, we investigated that polymorphisms in ABCB1, ABCG2 and ABCC3 could be a predictor for treatment response for osteosarcoma patients." (PMID 25097538, 2014).
osteosarcoma (continued). "Meanwhile, osteosarcoma cells with overexpressed TBL1XR1 had higher expression of stemness markers including ABCG2, BMI1, SOX2, NANOG, and OCT4, indicating that TBL1XR1 endowed osteosarcoma cells with stem cell-like properties." (PMID 38347836, 2024). "EID3 overexpression not only improved stem cell phenotype but also enhanced the enrichment of CD133+ cells and the expression of stem cell-related markers OCT3/4, ABCG2, and NANOG in osteosarcoma cells." (PMID 36071872, 2022). "In another study, primary human osteosarcoma samples had 3.9% side population cells which overexpressed ABC transporters, including ABCA1, ABCB1, ABCB2 and ABCG2 that contribute to multi-drug resistance." (PMID 30847027, 2019). "In both osteosarcoma cell lines investigated, promoter methylation levels of ABCB1 and ABCG2 were in the range from 10 to 17%." (PMID 27689338, 2016). "In osteosarcoma, a CD133+/ABCG2+/SP+ subset was enriched for cells with CSC features, such as the formation of spheres/clusters in serum-free medium with high clonogenic efficiency." (PMID 21264259, 2011). "These lung metastases had more cells positive for the markers CD117, Stro-1, ABCG2, and CXCR4 than the primary bone tumor, suggesting that the osteosarcoma CSCs are the cells with an increased ability to metastasize to lung." (PMID 20979639, 2010). "Nevertheless, these SSEA-4+ cell-containing xenografts hardly expressed any Stro-1, CD117, ABCG2 or CD133 that were shown to label TICs evident in several osteosarcoma cell lines 27, 28, nor did these xenografts contain any Hoechest-expelling side population." (PMID 25853231, 2015). "Although there is currently no strong evidence of their contribution to osteosarcomas treatment, other candidate genes such as DHFR, ABCC1 or ABCG2 should be investigated in future studies with large samples." (PMID 39771563, 2024).
breast tumors (27 papers, 2011 to 2025). "Interestingly, the expression of genes (GFRA1, ID1, ABCG2) implicated in the regulation of hematopoietic progenitor cells was found to be elevated in bone metastases compared with the primary breast tumors that had relapsed to bone." (PMID 23174366, 2012). "Therefore, other mechanisms, like the decreased proliferation rate, EMT, or the expression of negative regulators of apoptosis, may be implicated; although MDR1 and ABCG2 were up-regulated in RANKhigh ER+HER2- human breast tumors." (PMID 32477461, 2020). "BAX, BCL2, NFKB1 and ABCG2 genes expression were compared by using breast tumor tissues on TCGA-BRCA." (PMID 41154846, 2025). "ABCG2 expression in breast tumour cells was correlated with lymph node metastasis and clinical stages based on the analysis of invasive ductal breast carcinoma specimens from 196 patients." (PMID 33801148, 2021). "The discovery of ABCG2 is related to the resistance of breast tumours to chemotherapeutic agents such as anthracyclines, hence its name Breast Cancer Resistance Protein (or BCRP)." (PMID 35011695, 2021). "Nevertheless, ABCG2 expression in the tumour of TNBC patients was elevated and associated with a longer disease-free interval and OS in another study involving 124 primary breast tumour specimens." (PMID 33801148, 2021). "This was further confirmed by immunofluorescence, where spheroids were labelled with CD44+/CD24−/low/ABCG2/KI67 for CSCs derived from breast tumors, and CD133+/CD44+/ABCG2/Ki67 for prostate and ovarian tumors; except for the prostate LnCap CSCs, which were not CD44+." (PMID 28536422, 2017). "Other methods to isolate CIC such as dye exclusion mediated by the membrane transporter, ABCG2, or high expression of aldehyde dehydrogenase (ALDH) also appear to gate a subset of breast tumor cells with the capacity to initiate tumors in a mouse model." (PMID 21935375, 2011). "Similarly in breast tumor cells, osteopontin may activate the hedgehog pathway and enhance drug resistance through GLI1-dependent regulation of ABCB1 and ABCG2." (PMID 27400751, 2016). "For this purpose, we purified bCSCs flow-cytometrically from primary breast tumors on the basis of the cell surface phenotype CD44+/CD24-/low and confirmed their stemness properties on the basis of the expression levels of the following markers: MRP1 and ABCG2, ALDH1, and Oct-4, Sox-2, and Nanog." (PMID 25315241, 2014). "Additionally, in breast tumours ABCG2 expression was not significantly altered in olaparib naïve or resistant tumours but was significantly different between adenocarcinoma and metaplastic spindle cell carcinoma, suggesting that ABCG2 expression is phenotype dependent." (PMID 40874518, 2025).
multiple myeloma (27 papers, 2011 to 2025). "In another research, berberine-treated MCF-7 and baicalein-treated myeloma cells were associated with a decrease in expression of ABCG2 relative to untreated cells." (PMID 34400945, 2021). "Demethylation of ABCG2 was observed and negatively associated with ABCG2 protein expression in mitoxantrone-resistant multiple myeloma cells." (PMID 25401518, 2014). "To establish a pyrosequencing assay for ABCG2 we used a study of Turner and colleagues as reference in order to analyze the same CpG sites in the ABCG2 promoter, because methylation of these CpG sites was shown to be associated with ABCG2 expression in multiple myeloma." (PMID 24380367, 2013). "Inhibition of PI3K/AKT signaling pathway by agents like LY294002 or rapamycin has been shown to reduce ABCG2 expression in human multiple myeloma (MM) cell lines, suggesting that PI3K/AKT signaling positively regulates ABCG2 levels." (PMID 39931465, 2025). "The mRNA and protein levels of ATP-binding cassette transporter protein G2 (ABCG2) were elevated in myeloma adriamycin chemotherapy-resistant cells." (PMID 35615158, 2022). "In human multiple myeloma, the expression of ABCG2 is regulated by the PI3K/Akt signaling pathway, which affects the drug resistance of cancer cells." (PMID 34659526, 2021). "In this respect, the promoter methylation status of ABCG2 under basal conditions or in response to chemotherapy was reported to control BCRP expression levels in multiple myeloma cell lines and patient samples." (PMID 33476303, 2021). "The proportion of SP cells decreased in a dose-dependent manner and the expression of ABCG2 in myeloma cells was significantly repressed by baicalein treatment." (PMID 27338343, 2016). "ABCG2 transcripts were significantly enhanced in SP cells in comparison to MP cells in both myeloma cell lines." (PMID 25915427, 2015). "The efflux transporters ABCB1 and ABCG2 have been demonstrated to interact with tyrosine kinase inhibitors (TKIs) such as dasatinib, and to reverse drug-resistance in human multidrug-resistant multiple myeloma cells mediated by Src inhibition." (PMID 35164068, 2022). "Hh signaling in myeloma leads to activation of the ABCG2 drug efflux pump, which may render MMSCs treated with Hh inhibitors more sensitive to doxorubicin, lenalidomide and other myeloma drugs that are substrates of drug efflux pumps." (PMID 26415231, 2015). "Furthermore, FT has been found to negatively affect the activation of PI3K/AKT cascade that can regulate ABC subfamily G member 2 (ABCG2) expression and mediate chemoresistance in myeloma cells, and we also observed a similar effect on PI3K/AKT axis in our experiments." (PMID 31284669, 2019). "In the multiple myeloma cell line U266, the ABCB1 promoter was found to be slightly methylated, that of ABCG2 was < LOQ." (PMID 27689338, 2016). "Inhibition of AKT or knockdown of β-catenin in NEK2A-overexpressed myeloma cells inhibits the expression of ABC transporters ABCB1, ABCC1, and ABCG2; moreover, there was a decreased efflux of the hydrophilic eFluxx-ID gold fluorescent dye in those cells." (PMID 25705694, 2015).